AKT1 (AKT serine/threonine kinase 1)
Diseases named in the same sentence as AKT1 in open-access papers (continued):
Sharing a sentence is not in itself a finding about the gene and the disease.
meningioma (continued). "In this study, we screened 171 meningiomas using endpoint genotyping and linked mutations in AKT1 E17K and NF2 in grade I meningiomas to macrophage infilitration using four-colour flow cytometry and immunohistochemistry." (PMID 32070062, 2020). "Grade III meningioma are less likely to have TRAF7, AKT1, or SMO mutations, and exhibit genomic instability in the form of increased copy number variation." (PMID 32742192, 2020). "Next, we focused on the most common genetic alterations reported so far in meningiomas, including the NF2, SMARCB1, as well as TRAF7, AKT1, SMO, KLF4, PIK3CA, and TERT in non-NF2 mutated meningiomas." (PMID 31470906, 2019). "CDKN2A, ARID1A, BRCA1, NF1, and AKT1 were also commonly identified in meningioma samples across the cohort." (PMID 31191822, 2019). "Recently, alterations in other oncogenic genes such as TRAF7, AKT1, KLF4, PIK3CA, SMO, and DMD have also been implicated in meningioma etiology." (PMID 31191822, 2019). "Known mutations in genes including AKT1, TRRAF7, KLF4, and CDKN2A predispose to meningioma, including high grade meningiomas in the human WHO grading scheme." (PMID 31788444, 2019). "Other common driver mutations in our cohort such as CDKN2A, ARID1A, BRCA1, NF1, AKT1, SMO, PIK3CA have similarly been noted in various prior sequencing studies of meningiomas." (PMID 31191822, 2019). "Among the meningiomas, the most common mutations were in NF2 (59/71), PIK3CA (22/71), FGFR3 (13/71), SMO (11/71) and AKT1 (10/71), with Tertp (1/71) mutations the least frequent." (PMID 31565188, 2019). "To date, loss of the chromosomal region 1p and mutations in SMO, AKT1 and the TERT promoter are independent (cyto-)genetic predictors for meningioma recurrence." (PMID 31139260, 2019). "To date, loss of the chromosomal region 1p and mutations in SMO, AKT1 and the TERT-promoter are known as independent predictors for meningioma recurrence." (PMID 31139260, 2019). "These mutations are present in ~5.5% of grade I meningiomas, and are mutually exclusive with TRAF7, KLF4, and AKT1 mutations." (PMID 31970090, 2019). "Next, we focused on the most prevalent genetic alterations reported in meningiomas so far, including NF2, SMARCB1, as well as TRAF7, AKT1, SMO, KLF4, PIK3CA, and TERT in non-NF2 mutated meningiomas." (PMID 31470906, 2019). "Exclusive of TRAF7, AKT1, PIK3CA, KFL4, and SMO, mutations in POLR2A, which encodes DNA-directed RNA polymerase II subunit RPB1, are found in 6% of meningiomas." (PMID 31970090, 2019). "Approximately 70% of TRAF7/AKT1 meningiomas are in the anterior fossa or median middle fossa, and 20–30% are located in the anterior convexity." (PMID 30082628, 2018). "The tumor location changes according to the mutation type: anterior fossa, median middle fossa, or anterior calvarium for TRAF7/AKT1 and SMO mutated meningiomas; lateral middle fossa and median posterior fossa for TRAF7/KLF4-mutated meningiomas." (PMID 30279357, 2018). "In the non-NF2 meningiomas it was observed the frequent mutation of TRAF7, a proapoptotic ubiquitin ligase; a part of these meningiomas with mutated TRAF7 exhibited also KLF4 (a transcription factor involved in pluripotency) and AKT1 mutations." (PMID 30279357, 2018). "Several biological pathways in meningioma oncogenesis, including loss of NF2 and mutation of AKT1, are postulated to exhibit their oncogenic effects through activation of the mTOR mitogenic pathway, leading to uncontrolled neoplastic growth." (PMID 28923059, 2017). "mTOR pathway inhibitors are under clinical trial in recurrent and progressive meningiomas with AKT1 or PI3K pathway alterations." (PMID 28713588, 2017). "We also performed Sanger sequencing to check for the presence of mutations previously reported in meningioma driver genes, including regions of NF2, AKT1, TRAF7, KLF4, SMO, and the TERT promoter." (PMID 28552950, 2017).
meningioma (continued). "As a result, most of the previously reported meningioma mutations (NF2, TRAF7, NOTCH2, SMARCB1, CHEK2 and AKT1) were also detected in this study." (PMID 28177878, 2017). "To date, the most common alterations in sporadic meningiomas are NF2 mutations or loss of 22q, with non-NF2 mutant meningiomas harboring mutations in in AKT1, TRAF7, KLF4, POLR2A and SMO16–18." (PMID 28775249, 2017). "Such an approach is now feasible in meningioma with the recent identification of AKT1, SMO, and PIK3CA mutations, which opens the door for targeted pharmacotherapeutics in ~20% of grade I meningiomas." (PMID 27458586, 2016). "AKT1 is encoding a key effector of PI3K signalling and has been found to be mutated in 10%–15% of meningiomas." (PMID 27429002, 2016). "Next-generation sequencing has characterized recurrent somatic mutations in NF2, TRAF7, KLF4, AKT1, SMO, and PIK3CA, which are collectively present in ~80% of sporadic meningiomas." (PMID 27458586, 2016). "TRAF7 mutations in meningioma co-occur either with mutations in Kruppel-like factor 4 (KLF4) or in other genes, including v-Akt murine thymoma viral oncogene homolog 1 (AKT1) or phosphatidylinositol-4,5-bisphosphate 3-kinase catalytic subunit alpha (PIK3CA) variants." (PMID 41372821, 2025). "Interestingly, meningiomas with mutations in TRAF7, KLF4, AKT1 and SMO, as well as POLR2A, were later described by Nassiri and colleagues to have a more favorable patient prognosis compared to other genetic driver mutations." (PMID 39273576, 2024). "The most common genetic aberration in meningiomas is functional loss of NF2 and occurs in both low- and high-grade meningiomas, whereas NF2-wildtype meningiomas are enriched for recurrent mutations in TRAF7, KLF4, AKT1, PI3KCA, and SMO and are more frequently benign." (PMID 38571886, 2024). "Meningiomas in the first group are devoid of NF2 alterations and chromosomal instability; may feature AKT1, TRAF7, or KLF4 mutations; have the best prognosis; and are expected to respond to cytotoxic drugs." (PMID 37296907, 2023). "Additionally, TRAF7 mutations instigate meningioma growth by acting in combination with one of various co-mutations such as KLF4 and AKT1." (PMID 38001599, 2023). "CNVs deleting NF2 on chromosome 22q are early events underlying Immune-enriched or Hypermitotic meningioma tumorigenesis, but Merlin-intact meningiomas encode SSVs targeting TRAF7, AKT1, or KLF4 that may be tumor-initiating." (PMID 36993679, 2023). "Furthermore, several disease-causing mutations, including NF2, TRAF7, KLF4, AKT1 and SMO, have been described in meningiomas and compounds specific for driver mutations are currently under investigation in clinical trials." (PMID 38102708, 2023). "Group 1 meningiomas have the best prognosis, are free of NF2 mutations and chromosomal instability, may include AKT1, TRAF7, or KLF4 mutations, and are predicted good responses to cytotoxic therapies." (PMID 38001599, 2023). "Indeed, missense mutations in TRAF7, KLF4, and AKT1 exist in 30%, 14%, and 12% of non-NF2 meningiomas, respectively." (PMID 38001599, 2023). "In addition, both AKT1 and KLF4 meningiomas demonstrated trending enrichment of the “PI3K/AKT signaling pathway”." (PMID 36937440, 2023). "Interestingly, AKT1 and KLF4 meningiomas expressed genes specific for PI3K/AKT signaling pathway, suggesting overlapping gene signatures between the two subtypes." (PMID 36937440, 2023). "Moreover, it is relevant to develop new GEMMs that explore targetable somatic mutations found in human meningiomas such as TRAF7, AKT1, and PIK3CA, among others." (PMID 38001599, 2023). "Notably, NF2-mutant meningiomas had a near-complete female predominance (n = 30/32, 94%) when compared to the balanced female–male incidence of AKT1-mutant tumors (n = 7/15, p = 0.0006)." (PMID 35943573, 2022). "Mutations in TRAF7, KLF4, AKT1, or PIK3CA are commonly associated with grade 1 meningioma, whereas combined mutations might be associated with a high recurrence rate." (PMID 35712491, 2022).
meningioma (continued). "Importantly, FGFR2 and FGFR3 were detected in meningiomas, and FGF1 was shown to be able to stimulate meningioma cell proliferation by activation of AKT1 and STAT3." (PMID 35996584, 2022). "Moreover, some actionable mutations, including SMO, AKT1, and PIK3CA, regulate meningioma growth and are under investigation in clinical trials." (PMID 35565385, 2022). "The analyses here were initiated after diagnostic work-up of the tumors of a 47-year-old male patient with two independent meningiomas having identical somatic TRAF7 mutation N520S, but separate AKT1 (skull base, meningothelial) and KLF4 (convexity, secretory type) hotspot mutation." (PMID 35984495, 2022). "In contrast, meningiomas harboring an AKT1 mutation were predominantly located in the cervical spine (73.3%) and 87% of AKT1-mutant meningiomas (n = 13) (compared to 43.75% of NF2-mutant meningiomas, n = 14) arose ventrally or ventro-laterally to the spinal cord (p = 0.010)." (PMID 35943573, 2022). "Mutations common in non-chordoid low grade meningiomas, such as AKT1 and SMO, were also sparse or absent." (PMID 35440040, 2022). "Consistent with intracranial meningiomas, the histologic subtype of NF2-mutant meningiomas was variable (7 meningothelial, 16 psammomatous, 4 transitional, 5 fibrous), while all but 1 AKT1-mutant meningioma showed a meningothelial histology (93.3%, p = 0.0001)." (PMID 35943573, 2022). "In NF2 wild-type meningiomas, mutations in TRAF7, KLF4, AKT1, and SMO were noted." (PMID 34778063, 2021). "About 28% of meningioma at the middle anterior skull base, and, specifically, at the olfactory groove, have an impaired hedgehog pathway due to SMO mutations (L412F and W535L), which are mutually exclusive to AKT1 mutations." (PMID 34071391, 2021). "New GEMMs are needed in order to explore targetable somatic mutations found in human meningiomas, such as TRAF7, AKT1 or PIK3CA, where they will be essential for understanding the specific biological mechanisms involved and to provide accurate tools for preclinical drug evaluation." (PMID 34359639, 2021). "In contrast, we could not find in our WHO grade 1 tumors and control populations, non-synonymous genetic variants, for other genes previously reported to be recurrently mutated in meningiomas such as the TRAF7, AKT1, KLF4, TERT, and PIK3CA genes." (PMID 34868937, 2021). "As an exception, one patient presented with a psammomatous meningioma with a POLR2A mutation, and another patient presented with an angiomatous meningioma with a KLF4 mutation, while yet another patient presented with an atypical meningioma with an AKT1 mutation." (PMID 33772057, 2021). "AKT1 mutations result in downstream activation of the mTOR oncogenic pathway and SMO mutations cause activation of the Hedgehog signaling pathway rendering increased proliferation of meningioma cells." (PMID 32742192, 2020). "In a large cohort, mutations in AKT1 were identified in 38 of 300 non-irradiated meningioma samples (12.6%) and frequently occurred with TRAF7 mutations (25/38 tumors)." (PMID 33346248, 2020). "Genomic sequencing was also performed and mutations in NF2, TRAF7, SMO, KLF4, and AKT1 did not predict RB1 S780 staining or progression in grade 1.5 meningiomas." (PMID 33346248, 2020). "Moreover, mutations of NF2 are most frequent in fibroblastic/transitional meningiomas, KLF4 and TRAF7 in secretory meningiomas, and AKT1 mutations in grade I meningothelial meningiomas of the skull base and spine." (PMID 32244473, 2020).
meningioma (continued). "Interestingly, genetic abnormalities in meningiomas are different in relation to the location and the type of the lesion: in fact, SMO and AKT1-MTOR mutations are quite common in non-NF2, genomically stable meningiomas of the skull base." (PMID 32244473, 2020). "In this study, the presence of AKT1 and SMO mutations along with mutated MYBL2, both in the NF2-mutant primary atypical meningioma tumor and the derived cell line, proved that the meningioma-derived primary cell line had retained the genetic signature of the original tumor." (PMID 32742192, 2020). "Meningioma are the most common intracranial tumors and frequently linked with mutations in the PI3K catalytic subunit p110α isoform encoded by the gene (PI3KCA), or in the v-akt murine thymoma viral oncogene homolog 1 (AKT1) gene." (PMID 30881374, 2019). "The AKT1 E17K reported in meningiomas constitutively activates the PI3K-AKT pathway." (PMID 29391485, 2018). "It is important to note that AKT1 and SMO mutations are selectively observed in a subset of non-NF2-mutated meningiomas (9% and 6% of cases, respectively); furthermore, PIK3CA mutations occurred in 7% of non-NF2-mutant meningiomas." (PMID 30279357, 2018). "Half of meningiomas that harbor SMO mutation are located in the anterior fossa and the remaining is located usually in the calvarium and median middle fossa similar to TRAF/AKT1 mutant meningiomas." (PMID 30082628, 2018). "The constitutively activating AKT1 E17K mutation was observed in 13% of sporadic meningiomas (4/30), but was absent in our cohost of radiation-induced tumors." (PMID 28775249, 2017). "While inactivating mutations in NF2 have been described in 30 to 60% of sporadic meningiomas, recent studies have shown that non-NF2 meningiomas harbor activating mutations in SMO (L412F and W535L), AKT1 (E17K), and KLF4 (K409Q), as well as inactivating mutations of TRAF7." (PMID 25347344, 2014). "A better understanding of the molecular drivers of tumor progression and recurrence, such as the roles of NF2, SMO, AKT1, TRAF7, and KLF4 mutations, will facilitate the development of targeted therapies, potentially improving outcomes for patients with atypical and anaplastic meningiomas." (PMID 41007735, 2025). "Although our SMO/SUFU mutant OGM patients were mostly >65 years old, our sample size may not be sufficient to confirm the predominance of meningiomas mutated by AKT1 in younger patients and SMO/wild type in older patients." (PMID 38672677, 2024). "In accordance with previous findings, mutations in SMO, KLF4, AKT1, PIK3CA, and TRAF7 were exclusive to the benign methylation class, suggesting that their presence could be used as a surrogate for the methylation profile to identify benign meningiomas." (PMID 37296907, 2023). "Therefore, there appears to be a strong locational difference (p < 0.0001), suggesting that AKT1-mutant meningiomas arising from the ventral cervical spinal arachnoid are genetically distinct from their intracranial counterparts, based on the relative absence of TRAF7 co-mutation." (PMID 35943573, 2022). "Progressive meningiomas harboring this mutation have been categorized in the NF2-exclusive pattern, that lacks NF2 mutation and associates with skull base localization and female sex, similarly to the two AKT1-mutated atypical meningiomas identified in this study." (PMID 33670055, 2021). "Further immunohistochemistry analysis comparing AKT1 E17K mutants to WHO grade I NF2-negative samples showed significantly lower levels of CD163-positive activated M2 macrophages in meningiomas with mutated AKT1 E17K, signifying a more immunosuppressive tumour microenvironment in NF2 meningiomas." (PMID 32070062, 2020). "In addition to the established association of meningioma with pathogenic aberrations in the tumour suppressor gene NF2, genomic analyses have identified genes including TRAF7, KLF4, AKT1, SMO, PIK3CA and POLR2A to possess recurrent mutations in low grade non-NF2 mutant meningioma." (PMID 33167358, 2020).
meningioma (continued). "In addition, recent genomic analyses of meningioma using next-generation sequencing have identified mutations in the TNF receptor-associated factor 7 (TRAF7), the Kruppel-like factor 4 (KLF4), the v-Akt murine thymoma viral oncogene homolog 1 (AKT1), and the smoothened (SMO) gene." (PMID 32742192, 2020). "Additionally, AKT1 is co-mutated in TRAF7-mutated meningiomas without KLF4 mutations." (PMID 41372821, 2025). "In meningiomas, in addition to histopathological features, alterations in NF2, AKT1, TRAF7, SMO, PIK3CA, KLF4, and SMARCE1 genes are recognised as key biomarkers in molecular classification." (PMID 41009755, 2025). "A meningioma is a tumor that originated from the meninges with alterations in NF2, AKT1, TRAF7, SMO, and PIK3C, and most meningiomas are benign." (PMID 38540119, 2024). "Other genetic alterations, exclusive of NF2 that are reported in sporadic adult meningiomas, include TRAF7, SMO, KLF4, AKT1 and PIK3CA." (PMID 39612013, 2024). "Few of these biomarkers are being studied in clinical trials to develop targeted personalized therapies, including a phase II trial (NCT02523014) to investigate drugs in AKT1-mutant, SMO-mutant, or NF2-mutant meningiomas." (PMID 38001599, 2023). "We can see from our analysis of keyword trends that some keywords related to meningioma molecular characteristics are gradually increasing, such as NF2 and AKT1." (PMID 36969005, 2023). "The 2021 WHO classification criteria incorporates 10 genes that are frequently altered in meningiomas, including NF2, AKT1, TRAF7, SMO, PIK3CA." (PMID 35712492, 2022). "The AKT1 mutant pathway has also been targeted in a case report of the use of AZD5363, a AKT inhibitor, in a patient with numerous AKT1 mutant meningiomas resulted in partial response followed by long-term progression free survival." (PMID 36033542, 2022). "Low-grade meningiomas can also present other genetic alterations, particularly affecting SMO, TRAF7, KLF4 AKT1 and PI3KCA." (PMID 34679551, 2021). "A proportion of meningiomas at the middle skull base (ranging between 2.1% and 24%, and between 8.6% and 11.8%, respectively) were reported to display TRAF7 and KLF4K409Q mutations, which co-occur in secretory meningiomas, and which may coexist with AKT1 mutations." (PMID 34071391, 2021). "A second subclass within this group contained AKT1 (n = 26), PIK3CA (n = 14) and SMO (n = 6) mutant meningiomas (total n = 46)." (PMID 33087175, 2020). "In order to gauge the impact of the KLF4K409Q mutation on cellular pathways, we performed transcriptomic analysis of 7 KLF4K409Q and 10 KLF4wt meningiomas (all WHO I° and AKT1 wildtype) matched by patient sex, age and tumor location." (PMID 32245394, 2020). "NF2 mutant meningiomas are in all grades including WHO grade II and III whereas SMO, TRAF7, TRAF7/AKT1 and KLF4 meningiomas tend to be WHO grade I." (PMID 30082628, 2018). "Meningothelial and transitional meningiomas are more frequently seen in SMO, TRAF7/AKT1, and TRAF7/KLF4 mutant tumors." (PMID 30082628, 2018). "Inhibitors of recently identified meningioma oncogenes, including AKT1, SMO, and PIK3CA, are now in clinical trial for recurrent and progressive meningiomas." (PMID 28923059, 2017). "A clinical trial targeting AKT1 and SMO is currently underway for progressive meningiomas (NCT02523014)." (PMID 27458586, 2016). "Inhibitors of SMO, AKT1, and PIK3CA hold promise as molecularly targeted pharmacotherapy in meningioma." (PMID 27458586, 2016). "Therefore, molecular validation of meningioma findings (e.g., NF2, AKT1, TRAF7) and an increase in both sample size and tumour subtype diversity are important for enhancing the reliability and generalizability of future studies." (PMID 41009755, 2025). "In summary, mTOR pathway activation via AKT1 or PIK3CA mutations promotes cell proliferation and acts together with TRAF7 dysfunction in meningiomas without KLF4 co-mutations." (PMID 41372821, 2025).